TNF (tumor necrosis factor)
Diseases named in the same sentence as TNF in open-access papers (continued):
Sharing a sentence is not in itself a finding about the gene and the disease.
tumor (continued). "TNF-α is an inflammation-related cytokine, which is related to drug resistance of tumor cells." (PMID 35477364, 2022). "Luminex-based multi-cytokine analysis in the peripheral blood of tumor-bearing mice on day 35 demonstrated elevated levels of inflammatory cytokines (IFNγ, IL-1β, TNFα and Il-17) in the HS diet cohort, while there were elevated anti-inflammatory IL-10 blood levels in the LS diet cohort." (PMID 35741331, 2022). "Hence, our study uncovers that increase in tumor growth following chronic administration of JWH-133 is associated with increased in endocannabinoid (AEA and 2-AG) and protein (CB2 and TNFα) levels in tumor tissues." (PMID 35242036, 2022). "Moreover, this biocomplex regulated the secretion of tumor-related cytokines (i.e., GM-CSF, TNF, and IL-6) and promoted the activation of immune cell surface markers (i.e., CD80+, CD86+, and CD40+)." (PMID 36059807, 2022). "In addition, TNF-α is known to increase tumor cell migration and invasion, and is involved in all steps of tumorigenesis." (PMID 35840633, 2022). "In addition, IRF4-dependent cDC2s were found to promote the growth of MC38 tumor cells and to inhibit the infiltration of Th1 and TNF-α–producing cells into the tumor." (PMID 35454882, 2022). "Studies have investigated that TANs can induce mesenchymal stem cells (MSCs) to transform into tumor-related fibroblasts (CAF) by secreting IL-17, IL-23 and TNF-α, activating the protein kinase B/p38 (Akt/p38) pathway and ultimately promoting the proliferation and metastases of tumor cells." (PMID 36230676, 2022). "For example, a lack of LC3-associated phagocytosis activates the STING signaling pathway through the production of self-antigens (dsDNA), which induces pro-inflammatory gene expression (IL-6, TNF-α) to polarizes TAMs into antitumoral M1-TAMs and inhibits tumor growth." (PMID 36419877, 2022). "While, the TNFα/NF-kappa B signaling was not the only pathway for CBX7 to inhibit the tumor growth in ccRCC, the underlying mechanism by which CBX7 modulates the cancer progression needs to be performed in the furture." (PMID 35342353, 2022). "Thus, the ablation of genetic NR2F6 strongly enhances the secretion of interleukin-2 (IL-2), interferon-γ (IFN-γ), and tumor necrosis factor-α (TNF-α) both at tumor sites and ex vivo, thereby promoting antitumor immunological responses." (PMID 35907841, 2022). "In addition, tumor necrosis factor (TNF) and interleukin-6 (IL-6) were found to be autophagy inducers that are associated with carcinogenesis and tumor progression." (PMID 36230955, 2022). "Type I IFNs could alter neutrophils into N1 phenotypes, which transform the pro-tumor properties of low neutrophil extracellular traps and TNF-α expression into anti-tumor milieus." (PMID 36168626, 2022). "These include chronic inflammation triggering cell transformation, stimulation of pro-inflammatory cytokines (IL-6, IL-8, and TNF), alteration of the tumor microenvironment, and production of reactive oxygen species (ROS) and nitric oxygen synthase (NOS) that can lead to DNA damage." (PMID 35678665, 2022). "Numerous in vitro studies examining cell types, such as IGROV-1, PEO1, SKOV3, and OVCAR3, have reported that tumor necrosis factor-alpha (TNF-α), IL-6, and IL-8 act as potent paracrine and autocrine signaling molecules that regulate cancer cell invasion, proliferation, and bulk tumor growth." (PMID 35326569, 2022). "Tumor necrosis factor (TNF) plays a role in many pathophysiological processes, especially in the different periods of cell growth, inflammatory and immune responses, as well as tumor progression and metastasis." (PMID 35494080, 2022). "Moreover, the key functional cytokines IFN-γ and TNF-α secreting tumor-infiltrating CD3+CD4+ T and CD3+CD8+ T cells increased significantly in the group treated with PMA-TCLV and aPD-L1 combination therapy compared with other groups." (PMID 35217574, 2022).
tumor (continued). "Collectively, our comprehensive TNFRGs analysis of patients with LUAD revealed that TNF could be involved in forming the diverse and complex tumor microenvironment, its clinicopathological features, and its prognosis." (PMID 36505472, 2022). "Collectively these data demonstrate that reduced cytotoxic activity via the perforin-granzyme pathway in the absence of NKG7 can be compensated by TNF-mediated tumor cell death due to hypersecretion of TNF by NKG7 deficient T cells." (PMID 35874669, 2022). "In addition, the proportion of tumor‐infiltrating CD8+ T cells as well as TNFα+ CD8+ T cells was significantly increased in Cbx1‐knockout tumors, indicating the enhanced CD8+ T‐cell antitumor immune response in Cbx1‐knockout tumors." (PMID 36310139, 2022). "Moreover, the TNF-α protein levels were increased in macrophages isolated from the tumor tissues of WT mice injected with B16F10 cells compared to KLK6−/− mice." (PMID 36552865, 2022). "Indeed, γδ T cells are a subset of cytotoxic T cells that produce TNF-α, leading to tumor elimination through their powerful effector function." (PMID 35572595, 2022). "TNF-α promotes angiogenesis, tumor progression, and metastasis." (PMID 35892729, 2022). "We demonstrate that TNFα increased VCAM-1 expression in the tumor tissue, which could be involved in the intra-tumoral stromal and endothelial invasion." (PMID 36290384, 2022). "TNF-α contributes to tumorigenesis by creating a tumor-supportive microenvironment." (PMID 35547942, 2022). "Therefore, referring to macrophage categorization, mast cells are divided into anti-tumor MC1 and pro-tumor MC2 based on TNF, granzyme B (GZMB), IL9, VEGF-A, and C-X-C motif chemokine ligand 8 (CXCL8) expression." (PMID 36726981, 2022). "In addition, the in vitro anti‐tumor analysis revealed that the ADP@SWNT/TNFα complex efficiently inhibited tumor growth under laser irradiation, suggesting synergy between the photothermal therapy and gene therapy." (PMID 34994069, 2022). "In a different study, SCFAs could enhance CAR T cell anti-tumor activity via mTOR activation and the production of effector molecules, including TNF-α." (PMID 36358860, 2022). "Additionally, these results are consistent with our understanding of CAFs and their role in suppressing anti-tumour immunity through modulation of primarily tumour necrosis factor α (TNF-α) and interferon γ (IFN-γ)." (PMID 36046842, 2022). "TNF must be used in combination with chemotherapy to increase tumor feeding arterial permeability and to increase tissue concentrations of chemotherapy; meanwhile, its metabolic inhibitors inactivate the downstream survival and inflammatory pathways to induce tumor apoptosis." (PMID 35844550, 2022). "They checked the effect of the presence of the anti-PD-L1 antibody on the activation of the tumor-associated macrophages (MΦ) via an evaluation of the expression level of costimulatory molecules such as CD86, interleukin 12 (IL-12), and tumor necrosis factor-α (TNFα)." (PMID 35954362, 2022). "MoDCs help to amplify the anti-tumor response by TNF-α and IL-12 production." (PMID 36230990, 2022). "Similarly, the in vivo analysis showed the inhibitory effect of the ADP@SWNT/TNFα complex on tumor growth and metastasis when triggered by NIR irradiation." (PMID 34994069, 2022). "In this context, mutation-specific CD4+ T cells were shown to infiltrate the tumor and to be required for clinical efficacy, most likely by releasing proinflammatory cytokines such as interferon-γ (IFNG) and tumor necrosis factor-α (TNFA)." (PMID 36303101, 2022). "Additionally, etoposides’ action leads to the release of pro-inflammatory cytokines, such as IL-8, TNF-α, and IL-1β, which, depending on the tumor cell line, is inhibited by quinolones." (PMID 35756639, 2022). "In previous studies, tumor-related genes TNF-α, VEGFA, and c-Myc were also regulated by HDAC1." (PMID 35053925, 2022).
tumor (continued). "Importantly, MnNP treatment in TBR5 mice also significantly increased expression of the inflammatory cytokine TNF-α in the tumor, indicating a shift in the tumor microenvironment." (PMID 35513776, 2022). "Since peripheral blood B cells of tumor bearing HNSCC patients also expressed decreased levels of the cytotoxic TNFSF ligands TNF, LT-β, FasL and TRAIL, we examined whether HNSCC patient B cells displayed diminished tumoricidal activity." (PMID 35392082, 2022). "In addition, our in silico findings revealed decreased TNF-α mRNA levels in tumor adjacent mucosa and tumor in comparison to healthy tissue levels, which was in congregation with decreased TNF-α mRNA levels obtained in PBMCs." (PMID 36429712, 2022). "When we systemically i.v. injected Bifidobacterium that could secrete INFγ and/or TNFα into tumor-bearing animals, high amounts of cytokines were detected in tumors, with little in the blood and thus no systemic toxicity." (PMID 34204302, 2021). "In summary, we found that although TNF plays an important role in promoting TLSs and tumor infiltration of B cells in tumors, this axis can simultaneously activate the pyroptosis pathway of myeloid cells, thereby inhibiting the antitumor response of myeloid cells." (PMID 34804944, 2021). "The factors such as TNF-α and TNF-γ released by the tumor may also cause chronic systemic inflammation and microthrombosis, which may cause abnormalities in platelet function and number." (PMID 34221972, 2021). "The higher levels of TNFα expression in the primary tumor tissues from MFBD mice compared to OOBD and CD mice could play role in the differences observed in metastasis." (PMID 34371939, 2021). "Notably, it was known that tumor necrosis factors such as TNF-α are involved in inflammation, apoptosis, and cell proliferation." (PMID 33804566, 2021). "Moreover, genetic silencing of LINC01559 and UNC5B-AS1 suppressed tumor growth and resulted in alterations in several signaling pathways, such as TNF signaling pathway, IL-17 signaling pathway, and transcriptional misregulation in cancer." (PMID 33390837, 2021). "In contrast, other studies reveal that a decreased production of TNF–α induces a tumor phenotype." (PMID 34069731, 2021). "IL-17 and TNF-α secreting Th17 cells were enriched in PCs: they may favor an immunosuppressive tumor microenvironment." (PMID 34830179, 2021). "A combination of IFN-γ and tumor necrosis factor (TNF) directly drove tumor cells into senescence." (PMID 34366891, 2021). "These anti-MUC1-CAR4 T cells showed anti-cancer activity against MUC1-expressing CCA cells by increased production of anti-tumor cytokines (TNF-α and IFN-γ), pro-apoptotic protein (granzyme B), and induction of CCA cell lysis both in 2D and 3D (spheroid) co-cultures." (PMID 33737613, 2021). "TMEM16A silencing could up-regulate the expression of TNF-α, thus promoting the TNF-α signal and eventually leading to the induction of apoptosis and inhibiting the growth of tumor." (PMID 33681289, 2021). "In contrast to IgG4, IgE cross-linking on densely displayed, overexpressed tumor antigens forming TAMPs40 may trigger effector cell activation and release of mast cell-derived mediators, such as TNF-α." (PMID 33628623, 2021). "Importantly TNF is known to be secreted by malignant cells as well as cells in the tumor microenvironment, and there is experimental evidence from a variety of models that TNF can promote the growth of tumors." (PMID 33373873, 2021). "Additionally, as NO and TNF-α are well-known cytotoxic mediators generated in vitro by macrophages against various tumor cell lines, we tested the effect of their neutralization on the ability of TAMs to kill tumor cells." (PMID 34205330, 2021). "Finally, TNF-α was elevated in all tumor types but was the highest in malignant MGTs compared to benign and metastatic lesions." (PMID 34869014, 2021). "In addition, tumor cells secrete versican, which stimulates TNFα production by monocytes via activation of TLR2." (PMID 33540543, 2021).
tumor (continued). "However, co-treatment with TNFα and IFNγ induced whole tumour cell apoptosis by 37.6% in STING KO mice." (PMID 34285232, 2021). "Besides, supplementation with a combination of fish oil and selenium increase soleus and gastrocnemius muscle mass and reduces IL-6, TNF-α, and myostatin levels in gastrocnemius of tumor-bearing C57BL/6 mice." (PMID 34199575, 2021). "The relationship between NF-κB and inflammationinduced tumourigenesis was investigated in a metastatic colon cancer mouse model where it was observed that injection with bacterial lipopolysaccharide resulted in metastatic tumour growth via an inflammatory mediator, TNF-α." (PMID 33776564, 2021). "TNF-α is a key pro-inflammatory cytokine, which exhibited a dual function in tumor progression." (PMID 34497832, 2021). "In addition, A2AR targeting with CRISPR/Cas9 resulted in almost complete resistance to NECA-mediated suppression of IFNγ and TNF production upon coculture with Her2-positive tumor cells." (PMID 34050151, 2021). "Indeed, our data demonstrated that Y111 triggered the up-regulated expression of CD107a on the surfaces of Vγ2Vδ2 T cells and selectively provoked their production of IFNγ and TNFα in the presence of PD-L1 expressing tumor cells." (PMID 34040604, 2021). "We also discuss the impact of microbiota on tumor development and manipulations of the TNF/LT system, which may be effective as anti-cancer therapy." (PMID 33917839, 2021). "It has been shown that minimizing the amount of TNFα targeting the vascular endothelium with Cys-Asn-Gly-Arg-Cys-Gly-TNFα (NGR-TNF), a fusion protein targeting the tumor vasculature, can activate the endothelial cells and enhance tumor infiltration by cytotoxic T lymphocytes." (PMID 33540543, 2021). "The NF-κB pathway maintains stemness by regulating many tumor-promoting inflammation-related cytokines, like tumor necrosis factor (TNF)-α, IL-1, IL-6, monocyte chemoattractant protein 1 (MCP1), cytochrome oxidase subunit 2 (COX2), and inducible nitric oxide synthase (iNOS)." (PMID 33917482, 2021). "Several pro-inflammatory cytokines observed to be massively upregulated in SARS-CoV-2 infection, such as IL-6 and TNF-α, are also tumour-promoting factors and therefore could alter the rate of cancer progression." (PMID 34830872, 2021). "However, all these responses are orchestrated by soluble mediators (e.g., chemokines and cytokines) including tumor necrosis factor alpha (TNF-α) and Interleukin-6 (IL-6) secreted by either host immune cells or tumor cells themselves." (PMID 34576335, 2021). "NK-92/5.28.z cells secreted high amounts of effector molecules such as granzymes, granulysin, and perforin upon interaction with RMS tumor cells, while the levels of secreted cytokines such as TNF-α, IL-2, IL-6, and IL-4 were minimal or below the detection limit." (PMID 33809981, 2021). "Further, mice given dexmedetomidine showed significantly lower tumor burden and TNF-α levels compared to the Control group 4 weeks after surgery, suggesting a possible role for dexmedetomidine to abrogate the SSR and therefore alleviate immunosuppression during the perioperative window." (PMID 34692497, 2021). "Thus, the production of type I IFNs and TNF-α by activated T cells is necessary to achieve their anti-tumor effects during successful anti-PD-1 treatment by remodeling MDSCs." (PMID 33414378, 2021). "We propose that general inhibitors of inflammation such as NSAIDs or inhibitors of specific pro-inflammatory cytokines such as TNFα and IL-1β—that are constantly present at the tumor site from the time of malignant transformation and onwards—should be considered for the treatment of BC patients." (PMID 33806906, 2021). "In BC, it may act as a tumor suppressor by recruiting immune effector cells when it is expressed at higher levels in the tumor than in the adjacent healthy tissues, while IL-1β, TNFα, IL-6, and interferon (IFN)γ upregulate CCRL2." (PMID 33670492, 2021).
tumor (continued). "Here, we also have verified TNF‐α as a crucial proinflammatory factor in tumor tissues, which can be derived from tumors of GC patients to activate neutrophils besides inducing the expression of B7‐H2, suggesting relative importance of TNF‐α in neutrophil activation and tumorigenesis." (PMID 34185422, 2021). "However, mice fed ATX after tumor initiation exhibited a faster tumor growth and increased plasma levels of IL-6 and TNF-α, showing the importance of a good antioxidant status prior to tumor initiation." (PMID 34677429, 2021). "The NF-κB signal pathway is the bridge between TNF and tumor promotion." (PMID 34079469, 2021). "A pro-inflammatory environment (IL1β and TNF) could stimulate tumor growth but also promote tumoricidal M1 macrophage activity." (PMID 34209203, 2021). "M1-like TAMs are activated by IFN-γ, lipopolysaccharide, IL-1β, TNF, and/or GM-CSF and can recognize and destroy malignant cells via phagocytosis and cytotoxicity, in addition to producing pro-inflammatory cytokines that stimulate anti-tumor immunity." (PMID 34603327, 2021). "Furthermore, HIVEP3 that functions as transcription factor is related to modulation of immunoglobulin gene rearrangement, cell survival and TNF-signaling as well as osteoblastic bone and tumor formation." (PMID 34348642, 2021). "Priming pro-tumor neutrophils with IFNγ and TNFα could convert them to tumor-suppressing cells even in the presence of G-CSF and IL-6 by restoring the PI3K and p38 MAPK signaling pathways." (PMID 34572138, 2021). "RBC adhesion was quantified in an in vitro human umbilical vein endothelial cell (HUVEC) assay under both normoxic and hypoxic conditions with administration of either lipopolysaccharide (LPS) or Tumor necrosis alpha (TNFα) to mimic the known inflammation in the tumor microenvironment." (PMID 33946824, 2021). "In fact, under this culture condition, CarMTs experienced highly elevated levels of both tumor-derived and NK cell-derived pro-inflammatory chemokines and cytokines, most importantly IL-8 and TNF-α, that have been shown to negatively affect cardiac contractility in vivo." (PMID 34925361, 2021). "Importantly, TNF-α is a cytokine that has the capability to suppress tumor cell proliferation and even to induce tumor regression." (PMID 34209842, 2021). "In orthotopic tumor models, systemic TNF alpha was sufficient to restore MHC-I expression on tumor cells and enhance response to ICI in mouse models, leading to tumor regression that was associated with lasting systemic anti-tumor immunity that prevented engraftment on repeated tumor challenge." (PMID 34277419, 2021). "Notably, except that a higher population of infiltrated CD8+ T cells, the levels of CD3+CD8+IFN-γ+ T cells and CD3+CD8+TNF-α+ T cells in tumor were significantly elevated by Oxa(IV)@ZnPc@M (+) + anti-PD-L1 treatment." (PMID 34262026, 2021). "Therefore, TNF‐α and the induced hemorrhage inside the tumor play a major part at the early stage of bacterial invasion of the tumor." (PMID 33854892, 2021). "Th1 cells could increase the expression of anti-tumor immunity genes to produce more IFNγ and TNFα in the lung." (PMID 34887858, 2021). "Tumor cells can also stimulate astrocytes in their direct vicinity to increase the production of inflammatory cytokines, such as tumor necrosis factors -α (TNF-α) and -1β (TNF-1β)." (PMID 34439289, 2021). "Mice treated with C-87 exhibited lower concentrations of the following pro-inflammatory cytokines in the tumor paw compared to vehicle-treated tumor-bearing mice: TNFα (p < 0.05), NGF (P < 0.05), IL1β (P < 0.05), IL4 (P < 0.05), IL28β (P < 0.001), IL33 (P < 0.01), MIP3α (P < 0.01)." (PMID 33469141, 2021). "Then, we determined the effects of continuous TNFα + IL-1β stimulation on tumor cell growth." (PMID 34072893, 2021). "TNF and Fas interactions have been reported to regulate macrophage polarization, however their functions in tumor remain unknown." (PMID 34185431, 2021).